RNVU1-31 (RNA, variant U1 small nuclear 31)
Gene: Small nuclear RNA gene on chromosome 1 (145,465,617 to 145,465,780, reverse strand). Ensembl gene ENSG00000270722.
Gene Ontology:
Molecular function: pre-mRNA 5'-splice site binding
Biological process: mRNA 5'-splice site recognition
Cellular component: U1 snRNP
Homologues: Paralogues in human: RNU1-1 (99% identical), RNU1-2 (99% identical), RNU1-27P (99% identical), RNU1-28P (99% identical), RNU1-3 (99% identical), RNU1-4 (99% identical), RNVU1-18 (99% identical), RNVU1-29 (99% identical), U1 (99% identical), RNVU1-28 (98% identical), RNVU1-7 (98% identical), RNU1-89P (96% identical), and 133 more.